TSLP (thymic stromal lymphopoietin)
Diseases named in the same sentence as TSLP in open-access papers (continued):
Sharing a sentence is not in itself a finding about the gene and the disease.
asthma (continued). "The pathogenesis of both T2 and non-T2 mediated asthma is affected by TSLP, which plays a part in the initiation and maintenance of the airway inflammation." (PMID 36463281, 2022). "In recent years, TSLP has been shown to be involved in the pathogenesis of allergic diseases such as asthma and atopic dermatitis, as well as inflammatory arthritis." (PMID 35159975, 2022). "While it is clear that TSLP plays a crucial role in asthma pathogenesis in adults, there is still a critical need to elucidate the role of this molecule in the pediatric population." (PMID 36245744, 2022). "TSLP expression is increased in patients with asthma compared to healthy controls and correlates with measures of the airway obstruction." (PMID 36292755, 2022). "To date, there have been few head-to-head studies of IL-25, IL-33, and TSLP expression in human asthma." (PMID 33945508, 2021). "TSLP is mainly produced by epithelial cells in allergic disorders such as asthma and atopic dermatitis [7,8,]." (PMID 34418598, 2021). "Humanized mAb against TSLP has been reported to lower the rates of asthma exacerbations in clinical trials when compared with placebo." (PMID 34305908, 2021). "The airway epithelium is usually the first line of defense that is exposed to inhaled allergens and pathogens, releasing alarmins (including IL-25, IL-33, and TSLP) to propagate the development and exacerbation of asthma." (PMID 35126350, 2021). "Airway ATP levels were increased and strongly correlated with elevated IL-25 and TSLP expression in type 2–high asthma patients." (PMID 33945508, 2021). "Previous studies have suggested the critical role of keratinocytic TSLP in the development of AD into asthma." (PMID 34522948, 2021). "On the other hand, the identification of biomarkers for good responders will permit to select the right patient at the right time of disease for anti-TSLP therapy thus contributing to move one step forward in the battle against severe asthma." (PMID 34608100, 2021). "Pathophysiological and inflammatory processes in T2-high asthma are represented by a high level of type 2 cytokines: IL-5, IL-4, IL-13, IL-25, IL-33, and thymic stromal lymphopoietin (TSLP)." (PMID 34070316, 2021). "TSLP represents one of the most suitable therapeutic targets for emerging biological treatments of severe asthma." (PMID 33922072, 2021). "In patients with asthma, TSLP drives a T2 lung inflammatory response, but it is also involved in non-T2 processes." (PMID 34440780, 2021). "In order to write this narrative review, a literature search was carried out using the PubMed database, and as search words, we chose ‘asthma’, ‘alarmins’, ‘TSLP’, ‘IL-33′, ‘IL-25′, ‘anti-alarmins’, and ‘tezepelumab’." (PMID 34572294, 2021). "Tezepelumab is a fully human anti-TSLP mAb that prevents interaction of TSLP with its receptor, thereby inhibiting downstream inflammatory pathways; tezepelumab has been used for the treatment of severe asthma in phase II trials." (PMID 34305927, 2021). "The epithelial cell–derived cytokines IL-25, IL-33, and thymic stromal lymphopoietin (TSLP) initiate type 2 inflammation in allergic diseases, including asthma." (PMID 33945508, 2021). "In this regard, it is also noteworthy that a positive correlation has been detected between the ILC2 number and TSLP levels in nasal biopsies from patients with severe asthma and chronic rhinosinusitis." (PMID 33922072, 2021). "The most pronounced effect concerning changes in TSLP mRNA expression after UPM exposure was noted in asthma group." (PMID 34168212, 2021). "Our study provided mechanistic evidence for two important asthma GWAS loci: the TSLP and 17q12-21 loci." (PMID 34629083, 2021). "We observed decreased mRNA expression of TSLP in asthma and decreased expression of IL-6 mRNA COPD in moMφs after the exposure to UPM." (PMID 34168212, 2021). "TSLP has recently emerged following phase 3 clinical trials as a promising therapeutic target for severe asthma." (PMID 34572965, 2021).
asthma (continued). "In addition, TSLP has been implicated in exacerbating airway inflammation induced by exposure to aeroallergens, and diesel exhaust particles and TSLP may be (partly) responsible for exacerbations of asthma upon exposure to environmental pollutants." (PMID 33808333, 2021). "TSLP, IL-25 and IL-33 are involved in the pathophysiology of allergic diseases, including asthma and atopic dermatitis, as they activate the Th2-dependent immune response." (PMID 34301307, 2021). "SNPs at the TSLP locus have been highly replicated in asthma GWASs, and TSLP is recognized as having an important role in asthma pathogenesis through its broad effects on innate and adaptive immune cells promoting Th2 inflammation." (PMID 34629083, 2021). "We demonstrated that previous history of exacerbation, blood eosinophil count, and tryptase and TSLP levels can be used as independent factors for predicting future asthma exacerbations." (PMID 33875671, 2021). "In patients with asthma, dendritic cells treated with thymic stromal lymphopoietin (TSLP) secrete sEVs containing OX40 ligand." (PMID 33540806, 2021). "Of note, BALF ATP levels were strongly correlated with airway IL-25 and TSLP expression in asthma patients." (PMID 33945508, 2021). "In asthma, increased TSLP concentrations are observed in bronchoalveolar lavage, induced sputum, exhaled breath condensate, and plasma." (PMID 33875671, 2021). "Within this endotypic context, a key pathophysiologic role is played by thymic stromal lymphopoietin (TSLP), an innate cytokine especially involved in type 2 eosinophilic inflammation, but also implicated in neutrophilic and paucigranulocytic asthma." (PMID 33922072, 2021). "These asthma therapies have been directed against interleukin 4/interleukin 13, thymic stromal lymphopoietin, CRTH2 antagonists, and the IL-3/5/GM-CSF axis, and bring the possibility of improved asthma control for patients with severe asthma." (PMID 33917396, 2021). "TSLP which is the upstream role in the asthma cascade, inhibiting its stimulating activity on dendric cells and innate lymphoid cells thus preventing the induction of type 2 cytokines (e.g., IL-5, IL-4, and IL-13)." (PMID 34440488, 2021). "In chronic rhinosinusitis with nasal polyps (CRSwNP), a disease related to asthma, various expression patterns of IL-25, IL-33, and TSLP in different populations and regions have been described." (PMID 33945508, 2021). "All these data support the critical role of IL-25, IL-33, and TSLP in asthma pathogenesis and type 2-driven inflammation." (PMID 34608100, 2021). "In conclusion, epithelial miR-206 regulates airway IL-25 and TSLP expression and type 2 inflammation in asthma by targeting the CD39–extracellular ATP axis." (PMID 33945508, 2021). "Our data on airway IL-25, IL-33, and TSLP expression in asthma patients provide evidence for the potentially novel therapies targeting these cytokines in China." (PMID 33945508, 2021). "Viruses trigger asthma exacerbations by damaging or necrotizing airway cells leading to the release of airway epithelial cell-derived cytokines, like thymic stromal lymphopoietin (TSLP), IL-25 and IL-33." (PMID 34266437, 2021). "Airway epithelial cytokines IL-25, IL-33, and TSLP play important roles in the innate immune response to allergens and promote Th2 immune responses in asthma." (PMID 35126350, 2021). "Co-exposure to HDM and benzo(a)pyrene has also been shown to enhance IL-33 and TSLP production in an asthma mouse model." (PMID 34977086, 2021). "Recent studies revealed that cytokines such as thymic stromal lymphopoietin (TSLP), IL-33, and IL-25, highly expressed in the airway epithelium, are implicated in human asthma." (PMID 33445787, 2021). "Tezepelumab (AMG 157) is a fully human anti-TSLP antibody with potential use in uncontrolled asthma." (PMID 35095572, 2021).
asthma (continued). "For example, in a proof-of-concept placebo-controlled phase 2a trial involving 550 patients with uncontrolled asthma, the use of an anti-TSLP antibody resulted in a significantly reduced rate of exacerbations." (PMID 33615121, 2021). "Similar to IL-33, TSLP and IL-25 can also be detected in increased amounts in the tissues of patients with asthma or atopic dermatitis, and genome-wide analyses demonstrate an association of these cytokines with allergic diseases." (PMID 33615121, 2021). "Airway ATP levels were markedly elevated and strongly correlated with IL-25 and TSLP expression in asthma patients." (PMID 33945508, 2021). "With regard to the pathophysiology of asthma, TSLP plays a very important role in the complex interplay between the innate and adaptive branches of the immune system." (PMID 34572294, 2021). "Tezepelumab is a human monoclonal antibody which binds to thymic stromal lymphopoietin (TSLP), an epithelium-derived alarmin that plays a relevant role in the pathogenesis of asthma, being an upstream effector T2-high pathobiologic pathways." (PMID 34389053, 2021). "We found that the long TSLP transcripts and BALF TSLP protein levels were higher in type 2–high asthma patients than in type 2–low asthma patients and control subjects." (PMID 33945508, 2021). "TSLP expression within the airways is correlated with the severity of asthma and airflow limitation." (PMID 34572294, 2021). "Thymic stromal lymphopoietin (TSLP), IL-33, and IL-25 can control the transition from AD to asthma and food allergy." (PMID 33806376, 2021). "Nowadays, available biological asthma therapy is reserved for T2-high asthma; it targets allergy molecules IgE and eosinophilic interleukins (IL-5, IL-4, IL-13, TSLP)." (PMID 34070316, 2021). "It is noteworthy that TSLP released from keratinocytes can exacerbate allergy-induced asthma and promote “atopic march” (the progression of atopic disorder to the development of allergy-induced rhinitis and asthma)." (PMID 34281281, 2021). "Thymic stromal lymphopoietin (TSLP) plays an important role in the pathophysiology of various allergic diseases that are mediated by T helper cell type-2 (Th2) responses, including asthma and atopic dermatitis." (PMID 34443392, 2021). "Reduced barrier function in the respiratory epithelium seems to play an important role in T2-high asthma, as microbes and allergens activate epithelial-derived alarmins, such as thymic stromal lymphopoietin (TSLP), interleukin (IL)-25, and IL-33." (PMID 34574009, 2021). "The aim of the study is to review the immunopathology and treatment efficacy for severe asthma and focused on new biological agents with benralizumab (anti-IL-5) and tezepelumab (anti-TSLP)." (PMID 34440488, 2021). "Our integrative multi-omics approach then revealed a molecular mechanism shared between childhood onset and adult onset asthma in the TSLP gene at chromosome 5q22, and an RV-specific mechanism for childhood onset asthma at the 17q12-21 asthma locus." (PMID 34629083, 2021). "Recently, the Biologics License Application (BLA) for the anti-thymic stromal lymphopoietin (TSLP) tezepelumab has been accepted and granted priority review for the treatment of asthma from the US Food and Drug Administration (FDA)." (PMID 34572466, 2021). "The fact that TSLP is an important cytokine that contributes to asthma has been demonstrated in clinical trials where blocking TSLP resulted in alleviation of asthma symptoms." (PMID 33808333, 2021). "Among the cytokines released by the damaged epithelium are included IL-33, IL-25, and thymic stromal lymphopoietin (TSLP), which are linked to T2 asthma, although their precise contribution is still unclear in humans." (PMID 34572281, 2021). "Omalizumab, dupilumab, and tezepelumab can directly modulate the ASM in asthma, by specifically blocking the interaction between IgE, IL-4, and TSLP, and their receptors are located on the surface of ASM cells." (PMID 34572466, 2021).
asthma (continued). "In severe asthma, tezepelumab, an anti‐TSLP antibody significantly reduced the annualized rate of asthma exacerbation." (PMID 34617355, 2021). "The role of TSLP and alarmins as early initiators of the inflammatory cascade in asthma pathogenesis has led to the development of novel targeted therapies, particularly against TSLP, with the aim of blocking the inflammatory pathway at the very beginning." (PMID 34608100, 2021). "In a mouse model of chronic HDM-induced allergic asthma and in an ovalbumin-induced asthma both in rats and in mice neutralization of TSLP with monoclonal antibodies decreased Th2 cytokine levels and prevented structural alterations in the airways." (PMID 34084159, 2021). "Alarmins such as thymic stromal lymphopoietin (TSLP), IL-25 and IL-33 can drive allergic inflammation in response to airway damage and their expression correlates with asthma severity." (PMID 34777398, 2021). "The relationships between periostin, TSLP, eosinophils, and IL-4 in asthma point to the links between periostin–TSLP and the Th2 response." (PMID 33203095, 2020). "Significant differences in sputum periostin and TSLP mRNA expressions were shown, with the highest values in asthma and the lowest in controls." (PMID 33203095, 2020). "Overwhelming evidence supports a central role for the three epithelial-derived cytokines, TSLP, IL-33, and IL-25, in asthma." (PMID 33255348, 2020). "So far, the most extensively studied alarmin as suitable target for novel biological therapies of asthma has been TSLP." (PMID 33329598, 2020). "Thymic stromal lymphopoietin (TSLP), which is a master regulator of Th2-driven inflammation, has been studied in various allergic diseases such as asthma and inflammatory bowel diseases (IBD)." (PMID 32413869, 2020). "The gene targets of both miR-155 and miR-15a include genes that have been previously associated with asthma susceptibility in published asthma GWAS including GSDMB and TSLP." (PMID 33291534, 2020). "Here, we summarize the unmet therapeutic need in severe asthma and the current treatment landscape, discuss the rationale for targeting TSLP in severe asthma therapy and describe the current development status of tezepelumab." (PMID 33059715, 2020). "The results of our study clearly demonstrated that moDCs from asthma are the richest source of TSLP, especially in triple co-culture and are the most potent responders for TSLP action." (PMID 32842623, 2020). "Mechanistic studies indicate that TSLP drives eosinophilic (including allergic) inflammation, neutrophilic inflammation and structural changes to the airway in asthma through actions on a wide variety of adaptive and innate immune cells and structural cells." (PMID 33059715, 2020). "Our study demonstrated that the main producers of airway TSLP are epithelial cells whereas in contrast with asthma DCs, even after co-stimulation with other cells, COPD DCs produce a very low amount of this cytokine." (PMID 32842623, 2020). "TSLP, IL-33, and IL-17A expression in moDCs are differently regulated by epithelium in asthma, COPD, and healthy subjects." (PMID 32842623, 2020). "Lastly, several studies have linked polymorphisms in epithelial alarmins TSLP and IL33 with the risk for asthma." (PMID 33255348, 2020). "Diesel exhaust particles increased mRNA and production of TSLP from bronchial asthmatic epithelial cells that isolated from bronchus of patients with asthma." (PMID 33379407, 2020). "In support of these findings, a number of studies have shown that TSLP expression is elevated in the airway epithelium and bronchoalveolar lavage (BAL) fluid of individuals with asthma and that it correlates with disease severity and loss of lung function." (PMID 33255348, 2020). "Upgraded levels of periostin and TSLP in serum, induced sputum (IS), and bronchoalveolar lavage fluid (BALf) have been reported in patients with asthma and chronic obstructive pulmonary disease (COPD)." (PMID 33203095, 2020).
asthma (continued). "Thymic stromal lymphopoietin (TSLP), IL-33, and IL-25 are three epithelial-derived cytokines with critical roles in asthma pathogenesis as they are potent activators of DCs and ILC2s, which act upstream in the T2 immune response cascade." (PMID 33255348, 2020). "Although anti-IL-5 treatment and anti-IL-4/IL-13 treatment are clinically available for treating eosinophil-dominant severe asthma, recent research has been mainly focused on molecules that are more upstream, such as thymic stromal lymphopoietin." (PMID 32326200, 2020). "STAT3 plays a vital role in lung inflammation and airway remodeling in asthma, and it has been well proved as the downstream signal of TSLP." (PMID 32117985, 2020). "Both in vitro and in vivo studies have demonstrated a strong link between TSLP expression and the production of IL-4, IL-5, and IL-13, which are central in the development of a T2 phenotype in asthma." (PMID 33255348, 2020). "A recent study in human blood and airway innate lymphoid cells from patients with asthma has suggested that TSLP is a mediator of corticosteroid resistance." (PMID 33050928, 2020). "This notion has led to an immense interest in targeting these epithelial-derived cytokines as a potential treatment strategy in asthma, and recent clinical trials blocking TSLP have shown promising results." (PMID 33255348, 2020). "An important role in the development of asthma belongs to the activation of bronchial epithelial cells and the induction of cytokine production, such as IL-33, IL-25, and thymic stromal lymphopoietin (TSLP)." (PMID 32395125, 2020). "Expression of TSLP is increased in the airways of patients with asthma and correlates with disease severity." (PMID 33050928, 2020). "Very strong correlations between local periostin, TSLP, eosinophils, and IL-4 in asthma point to the link between periostin–TSLP and Th2 response." (PMID 33203095, 2020). "TSLP is highly expressed in diseased tissues of patients with allergic diseases such as asthma and atopic dermatitis, and analysis using genetically modified mice revealed that the action of TSLP is required to produce antigen‐specific allergic conditions." (PMID 32211586, 2020). "Cytokine thymic stromal lymphopoietin (TSLP) plays a pivotal role in the pathogenesis of atopic diseases such as atopic dermatitis, allergic rhinitis, and asthma." (PMID 33379407, 2020). "Additional studies have revealed that topical exposure to TCS augmented the allergic response to an experimental allergen through a thymic stromal lymphopoietin (TSLP)-mediated signaling pathway in a mouse model of asthma." (PMID 32449871, 2020). "Recent results of studies targeting the alarmin TSLP and therefore both T2 high and low asthma have confirmed efficacy against acute attacks of asthma." (PMID 32903600, 2020). "Most patients with concomitantly elevated levels of sputum eosinophils, periostin, and TSLP also had also increased IL-4 and IL-13 concentrations (6/7 patients for both cytokines, which represents 50% of the asthma group)." (PMID 33203095, 2020). "Recently, asthma exacerbations were prevented by an anti-TSLP monoclonal antibody, making this therapy also available in tumor types, in which a proven tumor-promoting role of TSLP has been established." (PMID 33042121, 2020). "For more than ten years, TSLP has been described to play an essential role in the induction of type 2 immune response in various diseases, including asthma and atopic dermatitis." (PMID 32066836, 2020). "This highlights the importance of investigating the TSLP pathway further as a target for asthma therapy." (PMID 32714552, 2020). "A strong positive correlation between IS periostin and TSLP protein levels (r = 0.96) as well as mRNA expression level (r = 0.95) was found in patients with asthma." (PMID 33203095, 2020).